CREB1 (cAMP responsive element binding protein 1)
Diseases named in the same sentence as CREB1 in open-access papers (continued):
Sharing a sentence is not in itself a finding about the gene and the disease.
cancer (continued). "The intersection of differentially expressed genes (DEG) and our list of candidate genes, resulted in 12 elements including cancer associated genes (NRAS, MYC, and VEGFA), circadian drug targets (SOD2 and CES2) and core-clock and ECCN genes (AHR, CREB1, CSNK2A1, NFIL, NPAS2, NR1D1, and PER3)." (PMID 32295075, 2020). "Mounting evidence indicates that CREB1 exhibits oncogenic functions in cancer progression." (PMID 30674866, 2019). "Investigations indicates that CREB1 is involved in cancer cellular proliferation." (PMID 30425814, 2018). "Recently, some researches have indicated that CREB1 could regulate cancer progression through transcriptional modulation of microRNA." (PMID 30523220, 2018). "CREB1, on the other hand, could prove to be a novel gene since its inhibition could potentially reduce the growth of cancer cells in the breast by keeping the estrogen levels at check." (PMID 28607444, 2017). "Given the roles of miRNAs as regulators of gene expression in cancer development and progression, we hypothesized that they may play a part in modulating CREB1 expression." (PMID 25825983, 2015). "In general, cancer cells are relatively serum starved, and CREB1 is upregulated in cancer tissues." (PMID 26472185, 2015). "CREB1 (cAMP response element-binding protein 1) is a widely recognized transcription factor that belongs to the basic leucine zipper (bZIP) family of proteins and has been extensively investigated in various tumors due to its significant impact on cancer development." (PMID 40722651, 2025). "Since CREB1 functions in cancer signaling, together with data on the involvement of ABL1 and ERBB2 protein kinases in pathways in cancers, it suggests the presence of upstream cancer-associated tissue-specific transcriptional regulation in DLBC and THYM cancers." (PMID 37373333, 2023). "Therefore, reducing CREB1 activity is an additional promising MDR cancer therapeutic target." (PMID 36439493, 2022). "miR-1297 could exert cancer-suppressing role in GC, in part, by downregulating CREB1 or CDC6." (PMID 34821362, 2021). "Thus, these predicted interacting protein partners of CREB1 might be involved in the regulation of CREB1-mediated cancer progression and prognosis." (PMID 33921660, 2021). "Thus, it is more likely that CREB1 promotes the PI3K-Akt pathway in cancer cells." (PMID 34641874, 2021). "In this comparison, the CREB1, FOS, HSPA5, and JUN genes exhibited a significant downregulation in malignant tumors compared to group 1 (p < 0.05) (Analysis 1)." (PMID 40722651, 2025). "In conclusion, CAFs regulate the symmetric division of OCSCs as well as the dedifferentiation of bulk cancer cells to OCSCs through secretion of Wnt5a, which acts via its co-receptor ROR2, on neighboring cancer cells, phosphorylating PKC and CREB1." (PMID 38191909, 2024). "The oncogenic factor LINC01857 promotes H3K27Ac and CREB1 transcription by promoting the enrichment of CREBBP in the CREB1 promoter region, thereby promoting cancer progression." (PMID 37901333, 2023). "Survival analyses in individual cancer cohorts verify the poor prognosis in patients co-expressing nuclear and mitochondrial targets of ATF1/CREB1, confirming the clinical relevance of ATF1 coordinated nucleus-mitochondria program." (PMID 37463926, 2023). "Follow-up studies indicated that miR-585-5p targets the downstream molecules CREB1 and MAPK1 to regulate the transcriptional and post-translational regulation of MITF, respectively, thus controlling its expression and cancer-promoting activity." (PMID 36268034, 2022). "CREB1 activates MITF transcription, and MAPK1 enhances the activity of MITF via phosphorylation at serine 73, boosting the cancer-promoting effect of MITF in GC." (PMID 36268034, 2022). "Together, the identification of EWSR1-ATF1 and EWSR1-CREB1 fusion underscores the critical role of constitutive CREB1/ATF1-mediated gene transcription in the development of CCSST and other CCS-like cancers that lack effective therapies." (PMID 36041632, 2022).
cancer (continued). "In the PPI network, the core targets, including AKT1, CREB1, CDC42, SIRT1, PIK3CA, and MMP9, are key cancer‐related genes, which further indicate the important role of miR‐204‐5p in human cancers." (PMID 35908280, 2022). "Altogether, we conclude that CREB1 regulates expressions of targets positively in most cancer types except SARC and STAD, in which CREB1 appears to upregulate and downregulate distinct sets of genes simultaneously." (PMID 34641874, 2021). "STRING and Cytoscape analysis presented four genes, PTEN, CREB1, CASP3, and SMAD3 as the key genes involved in cancer development." (PMID 34155232, 2021). "Zrt- and Irt-like protein 4 (ZIP4) can facilitate the growth of cancer cells and the EMT process via regulating cyclic AMP-responsive element-binding protein 1 (CREB1) and zinc finger E-box binding homeobox 1 (ZEB1), respectively." (PMID 32756339, 2020). "Above results verified a positive correlationship between CREB1 and RRM2 in clinical CRC specimens, which is involved in cancer progression and indicates a poor prognosis for CRC patients." (PMID 27801665, 2016). "Notably, among the 14 TFs whose binding sites were sex-dependently enriched across different cancers, eight were previously found to be enriched among sex-biased expressed genes, including SP1, ETV1, ELF1, E2F1, CREB1, CTCF, SIX2, and SOX2." (PMID 39716176, 2024). "In summary, our study has revealed a key pathway underlying NE gene upregulation by ADT, as well as established novel relationships between CREB1 and REST, and between EZH2 and REST, which may also have implications in other cancer types and in neurobiology." (PMID 37886478, 2023). "CREB1 has not been specifically interrogated as a drug target in these cancers, but our analysis corroborates existing research that it plays a crucial regulatory role in autonomic tumors by recovering it from two separate feature sets." (PMID 37242535, 2023). "In the current work, an aberrant increase in CREB1 phosphorylation was observed in MDR cells, and inhibition of CREB1 decreased ABCB1 expression and activity, indicating that CREB1 is a viable target for MDR reversal in cancer therapy." (PMID 36439493, 2022). "According to the regulation efficacy data, the positive regulation of TRIM15 and NHERF1 by CREB1 was reversed from normal to cancer; the negative regulations of TCEAL2, RBPMS2 and FAM20C by CREB1 disappeared; and the negative regulation of FERMT2 was reversed from normal to cancer." (PMID 35421923, 2022). "Therefore, PAAD was introduced as a possible cancer type following infection with (SARS-Cov-2 family), where the SMAD3, PTEN, CREB1, and CASP3 are overexpressed simultaneously." (PMID 34155232, 2021). "Moreover, we extract a CREB1 concordantly regulated gene list by applying RRHO analysis with both our data and RNAseq data of cancer patients from TCGA." (PMID 34641874, 2021). "Additionally, cAMP responsive element binding protein 1 (CREB1), known as a transcription factor participating in the metabolism and DNA repair, has been demonstrated to be cancer-promoting in various malignancies, including GBM." (PMID 32280303, 2020). "In addition, astragaloside IV can upregulate the levels of miR-134, which targets CAMP-responsive element-binding protein 1 (CREB1), consequently suppressing EMT and sensitizing cancer cells to oxaliplatin." (PMID 33066509, 2020). "Hence, there is increasing evidence to suggest that binding of CREB-1 to CRE in the RFC promoter is an important contributor to the induction of RFC gene expression in cancer cell lines and malignant tumors." (PMID 21760912, 2011). "Moreover, ssGSEA analysis with transcription factor gene sets in 1019 human cancer cell lines (The Cancer Cell Line Encyclopedia, CCLE dataset) indicates that CRE transcription factor (ATF1 and CREB1) activities are positively correlated with MYC targets, NRF1 targets and stemness scores." (PMID 37463926, 2023).
cancer (continued). "MBNL1 was not regulated by CREB1 in normal, while positively regulated by CREB1 in cancer." (PMID 35421923, 2022). "However, due to the essential function of CREB1 in normal and some cancer cells, CREB1 knockout via CRISPR/Cas9 has not been quite successfully established." (PMID 34641874, 2021). "Whereas in cancer cells, there might be more genes constitutively regulated by CREB1 regardless of cAMP activation." (PMID 34641874, 2021). "CREB1 is a member of the leucine zipper family of CRE sequence binding proteins that has been shown to play an important role in cellular growth, proliferation, and may contribute to the development of cancer." (PMID 27125827, 2016). "For example, the following top 100 MDS genes can be mentioned that are not yet covered by approved or experimental cancer or antineoplastic drugs [according to DrugBank, DGIdb, FDA6, HMDB, Tocris7, GeneCards databases]: GRB2, SOS1,SOS2, SHC1, GNB1, CREB1, GNG2, GNAQ, GNB5, GNAI2." (PMID 30728774, 2019).
infection (99 papers, 2008 to 2026). The state of being infected such as from the introduction of a foreign agent such as serum, vaccine, antigenic substance or organism. "Four genes previously thought to influence the severity of Guillan–Barré syndrome (GBS) were affected differently but moderately (PTGS2, Fc.: 1.188×; ANXA3, Fc.: 1.31×; CREB1, Fc.: 1.73×) by the 3rd hour of infection." (PMID 38787238, 2024). "Live EBOV or trVLPs infection resulted in an obvious accumulation of CREB1 in VIBs coexisting with VP35, NP, L, and 3′ leader region of viral genomic RNA, which is essential for viral RNA replication." (PMID 35474062, 2022). "Following a standard infection method, we obtained corresponding CREB1 rescue cells for all three KO clones." (PMID 34641874, 2021). "Our data concur with the transcriptomics results in detecting activation of β-catenin at 6 h post-infection and CREB1 (at 12 h for the antibody microarray data, and 24 h for the transcriptomics data)." (PMID 28480889, 2017). "Knockdown of Pthlh reduced the proliferation, transcription of known target genes and the levels of pCREB1, and surprisingly, total CREB1 in OS cells at early time points post infection." (PMID 27070462, 2016). "However, even with sparse infection, there was still strong knockdown of CREB1 in all BFP+/GFP+ nuclei at the level of individual cells, suggesting that transduction by an AAV at low MOI (potentially a single sgRNA) is sufficient for knockdown." (PMID 37398301, 2024). "Notably, the cellular distribution pattern of CREB1 was significantly changed to the cytoplasm by infection." (PMID 38445884, 2024). "In support of this observation, CREB1 was further demonstrated to be colocalized and associated with viral VP35 and NP in VIBs after EBOV or EBOV trVLPs infection." (PMID 35474062, 2022). "The list of transcription factors modulated by the infection includes the IRF, MYC-MAX, NFY, and E2F families; RELA; YY1; CREB1; and others." (PMID 37998351, 2023). "Moreover, the nuclear accumulation of phosphorylated CREB1 was also induced by Ad-VP35 expression, as well as EBOV or trVLPs infection." (PMID 35474062, 2022). "In the ileal network, JAK2 and CREB1, as well as SMAD2, SMAD3 and ERK2 (MAPK1) seem to play a central role in the intracellular PPI signalling driven by viral miRNAs and viral proteins, respectively, and JAK2 and both SMAD2 and SMAD3 were also upregulated upon infection." (PMID 35501398, 2022). "For example, the induction of the transcription factor CREB1 (cyclic AMP-responsive element binding protein-1) by the canarypox vector may qualitatively have improved the immune responses to Env in NHPs; it correlated with an increase in the number of SIV challenges needed for infection." (PMID 35384694, 2022). "Expression of EEA-1, CREB-1 and TNFRI proteins was selectively observed after macrophage infection with 2D6 bacteria but not in the vacuoles of macrophages infected with the wild-type bacterium." (PMID 20359357, 2010).
neurodegenerative disease (59 papers, 2013 to 2025). A disorder of the central nervous system characterized by gradual and progressive loss of neural tissue and neurologic function. "CREB1 has been linked to drug addiction, memory disorders and neurodegenerative diseases." (PMID 30323833, 2018).
psychiatric disorder (32 papers, 2011 to 2025). A disorder characterized by behavioral and/or psychological abnormalities, often accompanied by physical symptoms. "The protein–protein interaction analyses showed that CREB1 directly interacted with several risk genes of psychiatric disorders." (PMID 40535971, 2025). "In addition, prior work in GWAS association of pathways across psychiatric disorders has demonstrated that the protein encoded by CREB1 directly interacted with several risk genes of psychiatric disorders identified by GWAS66." (PMID 33057013, 2020). "The cyclic adenosine monophosphate (cAMP) responsive element-binding protein 1 (CREB1), as a junction of intracellular depression-related signal transduction pathways, is key to the cAMP signaling pathway, while this pathway has been found to be altered in most patients with psychiatric disorders." (PMID 36440424, 2022).
metabolic disorders (17 papers, 2013 to 2026). "We have therefore not only elucidated a potentially new mediator between CREB1 and skeletal muscle hypertrophy but also provided a potentially new target to treat muscle waste and metabolic disorders using technologies designed to manipulate DNA methylation at specific genomic loci." (PMID 34491915, 2021).
bacterial infection (5 papers, 2013 to 2025). "Research indicates that CREB1 plays a role in regulating the expression of Fc gammaRIIA, a receptor expressed on neutrophils and monocytes, which is crucial for combating bacterial infections." (PMID 40510586, 2025).
cardiovascular diseases (5 papers, 2013 to 2025). "Previous studies have shown that the transcription factor, CREB1, is involved in the pathophysiology of cardiovascular diseases." (PMID 34907172, 2021).
CREB1 also shares sentences with these, for which no sentence is quoted: ischemic stroke (26 papers); neurological disorders (23); non-small cell lung carcinoma (19); autism (14); brain injury (14); amnesia (11); injury (11); mental disorder (11); acute lymphoblastic leukemia (10); amyloidosis (10); Hepatic steatosis (9); myeloid leukemia (9); pulmonary fibrosis (9); cyst (8); Hypoglycemia (8); lymphoma (8); memory (8); multiple sclerosis (8); neurotoxicity (8); anxiety disorder (7); brain tumors (7); cognitive disorder (7); migraine (7); squamous cell carcinoma (7); subarachnoid hemorrhage (7); acute leukemia (6); dependence (6); mesothelioma (6); metastatic melanoma (6); steatosis (6).
A further 344 diseases each share a sentence with CREB1 in 6 papers or fewer.